PKD1 (polycystin 1, transient receptor potential channel interacting)
Diseases named in the same sentence as PKD1 in open-access papers (continued):
Sharing a sentence is not in itself a finding about the gene and the disease.
Renal cyst (continued). "Remarkably, we observed overall agreement in pre-cystic kidneys even between Pkd2 and Pkd1 models and juvenile and mature mice." (PMID 39666736, 2024). "Replicating our previous results, the upregulated gene sets in PKD1 renal cysts displayed a rich signature of mitogen-mediated proliferation." (PMID 39000280, 2024). "Cytokines, such as TNF-α, IL-6, and MCP-1, play crucial roles in renal inflammation within cystic kidneys, which can regulate the recruitment of macrophages in Pkd1 mutant kidneys." (PMID 39456148, 2024). "On the other hand, PC1 dosage-reduced Pkd1-cKO mice develop enlarged cystic kidneys that become very severe by P10 and leads to death due to renal failure." (PMID 38510176, 2024). "We have generated a comprehensive map of key metabolic pathways and regulators altered in PKD1 renal cysts." (PMID 39000280, 2024). "In certain genetic human cystic kidney diseases, such as autosomal dominant PKD (ADPKD) associated with PKD1 or PKD2 mutations, in vivo kidney cystogenesis is largely driven by cAMP signaling." (PMID 38788724, 2024). "In ADPKD, metabolic reprogramming and mitochondrial dysfunction are significant contributors to disease pathogenesis, modifying renal cyst growth in Pkd1 mouse models." (PMID 37845212, 2023). "Pyrimethamine, an antiparasitic compound, has been further tested in ADPKD preclinical models and was found to decrease cell proliferation in ADPKD patient-derived cultured epithelial cells and prevent renal cyst formation in Pkd1-KO mice." (PMID 37217845, 2023). "A renal-specific, DOX-inducible Pkd1 KO model (Pkd1fl/fl:Pax8-rTTA:TetO-Cre) was next used to determine if Tfeb was similarly affected in renal cysts that arise due to Pkd1 deletion." (PMID 36794754, 2023). "Gene expression showed EGF down-regulation (-5.6-fold, FDR = 0.001) and MCP1 up-regulation (3.1-fold, FDR = 0.03) in PKD1 renal cysts compared to MCT." (PMID 36342644, 2023). "Previous studies have reported structural and functional alterations in mitochondria within the cystic kidney epithelia of Pkd1 mutants, with implications for modifying renal cyst growth." (PMID 37845212, 2023). "The diagnosis of TSC2/PKD1-CGS is often based on the typical appearance of renal cysts (diameter exceeding 2 cm at an early stage) and variable coexistence with angiomyolipoma." (PMID 36979978, 2023). "In patient urine exosomes, murine PKD1 cystic kidneys, and human PKD1 cystic kidney tissue, miR-192-5p, miR-194-5p, miR-30a-5p, miR-30d-5p, and miR-30e-5p were significantly downregulated." (PMID 36766548, 2023). "For example, mice carrying heterozygous Pkd1 KO rarely exhibit renal cyst formation, and the manifestation of symptoms is limited in aged mice." (PMID 34980882, 2022). "In contrast, the PKD1insG/+ pigs produced in this study with a mutation introduced into exon 1 of PKD1 (c.152_153insG) by CRISPR-Cas9 exhibited a similar phenotype as human patients with ADPKD, including high penetrance of renal cyst formation." (PMID 34980882, 2022). "This was associated with an increased mRNA expression of Il1b, Tnf, Mcp1, Fn1, and Col1a2 genes in the cystic kidneys of Pkd1-miR Tg mice." (PMID 35955634, 2022). "As TSC2, the gene responsible for tuberous sclerosis, is adjacent to PKD1, the gene responsible for ADPKD, TSC2/PKD1 contiguous gene deletion syndrome is found in 2–5% of all tuberous sclerosis patients with renal cysts." (PMID 36362756, 2022). "Next, the inhibitory effect of PF‐06409577 on renal cyst progression in vivo was further investigated using neonatal kidney‐specific Pkd1 knockout mice (Pkd1flox/flox;Ksp‐Cre)." (PMID 35748097, 2022). "In our PKD1insG/+ pigs, PKD1-positive signals were observed in many epithelial cells forming the renal cyst walls." (PMID 34980882, 2022).
Renal cyst (continued). "It has been reported that cultured Pkd1-deficient cells express elevated levels of macrophage chemoattractants, including Mcp1 and Cxcl16, and both of these factors are able to stimulate macrophage migration, suggesting that they may contribute to the recruitment of macrophages to cystic kidneys." (PMID 35847973, 2022). "RNA-seq has identified a kidney-specific, evolutionarily conversed lncRNA called Hoxb3os that was highly expressed in renal tubules in adult wild-type mice but down-regulated in cystic kidneys from Pkd1 and Pkd2 mutant mice." (PMID 36203940, 2022). "The levels of PKD1 and PKD2 genes are associated with normal kidney development, and overexpression of these genes leads to renal cystic disease phenotypes." (PMID 36483738, 2022). "Pkd1, Pkd2 and Lgr4, genes involved in cystic kidney disease are now also known to play a role in Wolffian duct coiling." (PMID 35735916, 2022). "The authors analyzed the United Kingdom Biobank cystic kidney disease group and found probands with IFT140 loss-of-function variants as the third most common group after PKD1 and PKD2." (PMID 35832738, 2022). "Targeted disruption of the Pkd1 gene in principal cells leads to significant renal cystic disease, while such disruption in intercalated cells leads to a muted phenotype." (PMID 35625437, 2022). "In Pkd1-deficient mice, TAZ is expressed around the inner epithelial cells of renal cysts, and TAZ deletion reduces cyst formation." (PMID 36483738, 2022). "Further, an upregulation of glycolytic markers was observed, and the glycolytic signature was confirmed in a subset of human microarray data and cystic kidneys derived from hypomorphic Pkd1 mutant mice." (PMID 34901057, 2021). "By employing microarray expression profiling from cysts of different size and from minimally cystic tissue from five PKD1 human polycystic kidneys, the authors identified that a cross-talk of specific signaling pathways modulates renal cyst expansion." (PMID 34901057, 2021). "Five miRNAs from these two families, including miR-192-5p, miR-194-5p, miR-30a-5p, miR-30d-5p and miR-30e-5p, are validated to be downregulated in ADPKD patient urine exosomes, and cystic kidneys from Pkd1 mutant mice and ADPKD patients." (PMID 33809516, 2021). "Differentiation of these PKD1 or PKD2 mutant hPSCs into kidney organoids led to formation of large renal cysts instead of the tubular nephron-like structures." (PMID 33459801, 2021). "In vivo inhibiting effects of Y6 and Y10 on renal cyst development were determined in a kidney-specific Pkd1 knockout mouse (Pkd1flox/flox; Ksp-Cre, PKD) model." (PMID 35052542, 2021). "The loss of function of either PKD1 or PKD2 is sufficient to induce autosomal dominant polycystic kidney disease whereby affected individuals develop large and numerous renal cysts leading to renal failure." (PMID 33459801, 2021). "Furthermore, we found that the expression of genes associated with EVs/exosome biogenesis was upregulated in Pkd1 mutant renal epithelial cells and tissues, suggesting that abnormal secretion of cystic renal epithelial cell EVs/exosomes may occur in cystic kidneys." (PMID 34315885, 2021). "Ten weeks old Pkd1−/− mice demonstrated multiple renal cysts, which were more pronounced in males when compared to females." (PMID 34199520, 2021). "Renal cyst models of ADPKD using nephron organoids have been generated from gene-edited homozygous PKD1/2-mutant hESCs." (PMID 33656639, 2021). "Most molecular studies on cystogenesis have focused on ADPKD causing mutations in Pkd1 and Pkd2 genes (encoding PC1 and PC2, respectively) due to their epidemiological burden in comparison with other genes associated with renal cysts." (PMID 34828368, 2021). "In contrast, we recently generated nephron organoids from both ADPKD patient-derived and gene-edited heterozygous and homozygous PKD1-mutant hiPSCs to reproduce renal cyst legions by forskolin treatment." (PMID 33656639, 2021).
Renal cyst (continued). "Conditional mutations in PKD1 and IFT88 mice revealed that cilia dysfunction induced before postnatal day 12 (P12) resulted in a rapid onset of cystic kidney disease whereas, cystogenesis was remarkably prolonged if a ciliary loss occurred after P12." (PMID 34828368, 2021). "An unexpected finding was of reduced ciliation, in both the number of ciliated cells and the cilia length in PKD1 cystic cells, in PKD1 and Pkd1 cystic kidney tissue." (PMID 32663194, 2020). "A significant increase in total GTP-RhoA was detectable in PKD1 cystic cells compared with controls and confirmed in cystic kidneys of Pkd1 mice." (PMID 32663194, 2020). "We therefore examined if treatment with niclosamide and benzbromarone in vivo will inhibit enlargement of renal cysts in Pkd1−/− animals." (PMID 32859916, 2020). "Both Pkd1 haploinsufficiency and overexpression can result in renal cyst formation in mouse models, suggesting that the expression of the human PKD1 gene should be tightly controlled." (PMID 32724471, 2020). "The present data demonstrate the crucial role of TMEM16A for the growth of renal cysts in a mouse model for ADPKD and in Pkd1-deficient plMDCK cells in vitro." (PMID 32859916, 2020). "Remarkably, enhanced expression of CFTR in cystic kidneys is entirely reversible upon additional knockout of Tmem16a in Pkd1−/−/T16a−/− animals." (PMID 32859916, 2020). "Of interest, LTCC subunits (Cav1.2) are reported to be expressed in primary cilia, zebrafish cav1.2 morphants exhibit “cystic kidneys” and lentiviral Cav1.2 knockdown in Pkd1+/− mice resulted in severe PKD44." (PMID 31919453, 2020). "Although we observed significant deregulation of PCP in pre‐cystic kidneys after injury in both single Pkd1 mutant mice and double KO, the additional deletion of Fjx1 did not further change the PCP phenotype in the Pkd1 KO." (PMID 31038742, 2019). "Here, we describe a case of a dual mutation in PKD1 and GANAB genes with an early clinical presentation in a 12-year-old adolescent girl with renal cyst formation and nephrolithiasis; and discuss impacts of dual mutation on the severity of the disease." (PMID 30792735, 2019). "Because we identified a new cystogenic mechanism, we wished to compare Tsc renal cystic disease to Pkd1 renal disease." (PMID 30675765, 2019). "A cystic kidney disease panel should include adequate coverage of PKD1, PKD2, PKHD1, Daz-interacting zinc-finger protein 1-like (DZIP1L), HNF1B and genes for other ciliopathies such as nephronophthisis (NPHP) and Bardet–Biedl syndrome (BBS)." (PMID 31118499, 2019). "Mutations in the PKD1 and PKD2 genes, encoding the polycystin 1 and polycystin 2 Ca2+ ion channels, respectively, result in tubular epithelial cell-derived renal cysts." (PMID 28993480, 2017). "There is an interesting overlap with the localization and function of NPHP genes and other “cystogenes” such as PKD1, PKD2, and the many other inherited causes of cystic kidney disease." (PMID 29379777, 2017). "Renal cyst regression with sirolimus has been documented to occur in pcy mice and Pkd1 conditional null mice." (PMID 27723777, 2016). "To determine the timing of changes in signaling pathway activity following Pkd1 deletion, we assessed the behavior of a subset of the dysregulated markers in control and cystic kidneys at 14, 18, 21, 26, 64, and 180 days of age." (PMID 27356569, 2016). "The Pkd1V/V animals are viable with virtually normal appearing kidneys at birth, whereas Pkd1 null mice develop very severe cystic kidneys starting at e15.5 and are embryonically lethal." (PMID 26805887, 2016). "To determine if similar mechanisms are associated with cystogenesis in the Pkd1 cKO model, we compared the expression of markers related to cystogenic pathways in normal or cystic kidneys from humans and Pkd1 cKO mice." (PMID 27356569, 2016).
Renal cyst (continued). "A case with separate TSC1 and PKD2 mutations had a very modest cystic phenotype, probably due to the relatively mild disease in PKD2 compared to PKD1 and because TSC1 mutations are rarely associated with renal cysts." (PMID 26077033, 2015). "Additional supporting evidence implicating Kif12 as the Mpkd2 modifier gene candidate is provided by recent studies that demonstrate renal cystic disease-attenuating effects of Kif3a deletion in Pkd1 and Pkd2 mouse models." (PMID 26295839, 2015). "Analysis of TSC2 patients with severe renal cystic disease showed they can have deletions also disrupting PKD1; a contiguous gene syndrome (CGS)." (PMID 26077033, 2015). "We examined the molecular pathways that modulate renal cyst formation and growth in the Pkd1-/- model by performing global gene-expression profiling in embryonic kidneys at days 14.5 and 17.5." (PMID 21518438, 2011). "It should be taken into account, however, that overexpression of the human or murine PKD1 or 2 genes in mice is sufficient to induce renal cyst formation." (PMID 19863783, 2009). "While ADPKD is predominantly associated with PKD1 and PKD2 gene variants, there are documented cases where individuals with pathogenic variants in COL4A3, COL4A4, or COL4A5 also present with renal cysts and even a clinical diagnosis of polycystic kidney disease (PKD)." (PMID 40565535, 2025). "In rapidly and/or slowly progressive mouse Pkd1 models, Kcnn4 inactivation slowed renal cyst growth; attenuated PKD-stimulated cAMP and ERK/Myc signaling pathways; reduced PKD-associated ciliary elongation, cell proliferation, and fibrosis; improved renal function; and prolonged survival." (PMID 41122971, 2025). "However, we cannot exclude that this upregulation results from development of the renal cystic disease, which is consistent with increased expression of PKD1/Pkd1 gene in cystic epithelia of murine models and human ADPKD kidneys." (PMID 41166294, 2025). "Consistent with this, we also found increased expression of SIRT1 (1.4×) in human PKD1 renal cysts." (PMID 39000280, 2024). "The patient also had a PKHD1 VUS; however, the clinical presentation (large cystic kidneys, absence of liver cysts, and early kidney disease progression) is more consistent with the PKD1 variant as the more likely explanation for the disease." (PMID 37962562, 2024). "To understand AURKA’s role in regulating renal cyst development we conditionally deleted the gene in mouse models of Autosomal Dominant PKD (ADPKD) and Joubert Syndrome, caused by Polycystin 1 (Pkd1) and Inositol polyphosphate-5-phosphatase E (Inpp5e) mutations respectively." (PMID 38191531, 2024). "We hypothesize that increased expression of xCT could be an important mechanism of cysteine recruitment for the proliferation of PKD1 renal cysts." (PMID 39000280, 2024). "Cystic renal disease is most often ascribed within the heterogeneous group of chronic kidney diseases to ADPKD, which is determined by heterozygous pathogenic variants in PKD1 and PKD2 in the majority of patients." (PMID 38790225, 2024). "The patient's cystic kidney disease presentation was attributed to the truncating IFT140 variant rather than PKD1 VUS." (PMID 37962562, 2024). "This also applies to transgenic Pkd1-null mouse models that clearly develop renal cysts." (PMID 37579949, 2023). "Subsequently, non-truncating, previously unreported biallelic PKD1 variants were identified, but heterozygous parents did not have renal cysts on ultrasound." (PMID 37372410, 2023). "Pkd1 knockout mice develop severe cystic kidney and pancreas, culminating in embryonic lethality." (PMID 37845212, 2023). "Indeed, we found a significant down-regulation of EGF and up-regulation of MCP1 in both human and murine PKD1 cystic kidney tissues from previously published microarray data, and confirmed this by qRT-PCR of additional cystic samples." (PMID 36342644, 2023).
Renal cyst (continued). "The presence of these renal cysts does not affect the renal function, or cause end-stage renal disease, as seen in PKD1- and PKD2-caused ADPKD." (PMID 37628703, 2023). "They confirmed that miR-192-5p, miR-194-5p, miR-30a-5p, miR-30d-5p, and miR-30e-5p were significantly downregulated in the urine exosomes in both murine and human PKD1 cystic kidneys, and all were significantly correlated with baseline eGFR and ultrasound-determined mean kidney length." (PMID 37241147, 2023). "Mice either homozygous for the modified Pkd1 allele or having it “in trans” with a Pkd1 null allele were born at expected mendelian frequencies and aged normally without developing renal cystic disease." (PMID 37540694, 2023). "We describe two unrelated individuals with early onset cystic kidney disease and unaffected parents, where a combination of next-generation sequencing of cystic genes including PKHD1, HNF1B and PKD1 allowed the identification of biallelic PKD1 variants." (PMID 37372410, 2023). "In heterozygous Pkd1-KO mice, renal cyst formation is very rare, even at an old age29,30." (PMID 34980882, 2022). "Although Pkd1 and Pkd2 are direct miR-17-5p targets, miR-17-5p upregulated by c-Myc was also able to enhance proliferation in cystic kidneys from Pkd1 knockout (KO) ADPKD models, at least in part, by inhibiting mitochondrial oxidative phosphorylation through repressing Pparα." (PMID 36203940, 2022). "The gene dosage (haploinsufficiency) model hypothesizes that a reduction in PKD1 expression levels below a critical threshold leads to renal cyst formation." (PMID 34980882, 2022). "Renal cysts originate mainly from the collecting ducts in Pkd1 HOMO kidneys." (PMID 36611841, 2022). "miR-21 is also upregulated in cystic kidneys from Pkd1 conditional knockout mice (Pkd1flox/flox:Pkhd1-Cre mice), Pkd2 conditional knockout mice (Pkd2flox/flox:Pkhd1-Cre mice), and HNF1B conditional knockout mice (Hnf-1βflox/flox:Pkhd1-Cre mice), and in human ADPKD kidneys." (PMID 33809516, 2021). "Effect of dopamine receptor antagonist on renal cyst formation in Pkd1-KO mice." (PMID 33886508, 2021). "We observed no morphological changes of the kidneys from the Pkd1-, Pkd2-, and the Kif3a-KO mice 2 weeks after the induction (at the age of 8 weeks) and observed some dilated kidney tubules after 5 weeks of induction; renal cysts developed from 8 weeks of induction in Pkd1 and Pkd2 KO mice." (PMID 33886508, 2021). "Pkd1flox/+:Pkhd1-Cre mice with Pkd1 deletion in one allele developed normally with no renal cyst formation up to 1 year." (PMID 34315885, 2021). "While HT mice show almost exclusively Pkd1+/− renal cells but do not display cysts, reproducing the background cell environment found in ADPKD type 1 patients, CY mice have renal cysts presumably formed by Pkd1−/− cells, reproducing the ADPKD type 1 cystic phenotype and its expected consequences." (PMID 34611276, 2021). "In addition to the association seen with PKD1, we also saw a significant association between the related gene PKD2 and cystic kidney disease (CKD)." (PMID 34385667, 2021). "Knockdown of Pkd1 induces PKD with multiple renal cysts and enlarges kidneys." (PMID 32859916, 2020). "Conclusions: p68 plays a critical role in negatively regulating the expression of the PKD1 gene along with positively regulating the expression and maturation of miRNAs and activation of PKD associated signaling pathways to cause renal cyst progression and fibrosis in ADPKD." (PMID 32724471, 2020).